CCN3 (cellular communication network factor 3)
Diseases named in the same sentence as CCN3 in open-access papers (continued):
Sharing a sentence is not in itself a finding about the gene and the disease.
cancer (30 papers, 2004 to 2025). A tumor composed of atypical neoplastic, often pleomorphic cells that invade other tissues. "CCN3, however, has been reported to have negative regulatory properties, and its abnormal expression is associated with cancer progression." (PMID 24551846, 2014). "Since the discovery of this matricellular protein, CCN3 has been implicated in an increasing number of diverse biological processes including proliferation, differentiation and angiogenesis as well as pathological conditions such as fibrosis and cancer." (PMID 22427255, 2012). "NOV encodes the regulatory protein CCN3, which plays an important role in cancer development." (PMID 22142333, 2011). "CCN3 was first discovered as an overexpressed gene in myeloblastosis-associated virus type-1-induced nephroblastoma and has since been implicated in many diverse biological processes, such as proliferation, differentiation, angiogenesis and fibrosis, all of which promote cancer development." (PMID 33833779, 2021). "In addition, overexpression of CCN3 caused a decrease in cancer cell adhesion to collagen I and collagen IV, which might be due to decreased levels of α2β1 integrin." (PMID 22427255, 2012). "We further investigated the effect of CCN3 on cancer stem cell (CSC) formation, which are known to be related to the EMT and metastatic ability of cancer cells." (PMID 36737605, 2023). "This course can rationalize the presence of impaired CCN3 proteins in the nucleus of malignant cancer cells." (PMID 34940056, 2021). "“Complete” CCN3 (expression of all four of CCN3 domains) is an anti-proliferative protein but can be involved in cancer malignancy." (PMID 34940056, 2021). "Recently, interest in CCN3 has emerged for cancer research because of the protein’s central roles in cell regulation." (PMID 29061995, 2017). "By modifying this key cellular microenvironmental component CCN3 is thus able to deeply affect cancer growth both directly, affecting cancer cell behavior, and indirectly, affecting angiogenesis." (PMID 27809279, 2016). "Our previous work showed that CCN3 is highly expressed in malignant PCa cells and regulates cancer cell migration." (PMID 24721786, 2014). "What is clear is that CCN3 can play complex roles in modulating cancer phenotypes, such as metastasis, as it does in the regulation of normal cellular behavior." (PMID 22427255, 2012). "Several of these biological properties are shared by CCN3 whose expression was reported to be increased in malignant tumors, to interfere with adipocitic differentiation, and to be involved in the tumorigenic phenotype of CML." (PMID 16895594, 2006). "The CCN3 protein is detected in the nuclei of various cancer cell types, and this nuclear form of CCN3 is sometimes truncated, deprived of its amino-terminal part (and unpublished data)." (PMID 17049074, 2006). "The full-length secreted CCN3 exerts inhibitory effects on the proliferation of various human cancer cell lines, whereas an amino-truncated form deprived of the secretory peptide signal, was showing transforming activities on primary cells in culture." (PMID 17049074, 2006). "Preliminary results that have been obtained in various pathological situations aside from cancer, have also pointed CCN3 as a key regulator of potential interest in molecular medicine." (PMID 16504021, 2006). "An amino-truncated form of CCN3 devoid of signal peptide has been detected in the nucleus of cancer cells (and unpublished data)." (PMID 17049074, 2006). "In particular, CCN3, a scaffolding protein that controls and balances the interconnection between individual signalling pathways, is involved in numerous biological processes that promote cancer development." (PMID 38909013, 2024). "CCN3 was found to induce cancer by interacting with the EGFR signaling pathway in TNBC." (PMID 36737605, 2023).
cancer (continued). "We first assessed expression of CCN family members, CCN1, CCN2, CCN3 and CCN5 which have been implicated in modulating cell proliferation, cell adhesion, angiogenesis, cell migration, metastasis and epithelial-mesenchymal transition in a variety of cancers." (PMID 25541962, 2014). "Emerging evidence positions CCN3 as an important modulator of cancer progression and metastasis." (PMID 22427255, 2012). "Although it may not be effective for the treatment of cancers with yin–yang regulatory system deficiency, development of CCN3-based therapeutics for fibrosis and related diseases is highly expected in the near future." (PMID 35682564, 2022). "Furthermore, the aberrant expression of CCN3 is also involved in fibrosis and cancers." (PMID 34393649, 2021). "Given the effects CCN3 has on the differentiation and function of bone resident cells, it may not be surprising that CCN3 has been implicated in the progression of these cancers as well." (PMID 22427255, 2012). "Some extracellular proteins, including CCN3 and ECM1, have been suggested as stimulators of integrin/FAK for invasion and metastasis of cancer cells." (PMID 38355577, 2024). "Using the Cancer Cell Line Encyclopedia (CCLE) database and public databases, we found that CCN3 expression is upregulated in TNBC." (PMID 36737605, 2023). "The nephroblastoma overexpressed (NOV/CCN3) gene is a member of the CCN family of matricellular proteins that play an important role during inflammation, tissue repair and cancer." (PMID 34064989, 2021). "Altered expressions of CCN1/CYR61, CCN2/CTGF, CCN3/NOV, and CCN4/WISP1 were found to correlate with clinical features, including venous invasion, cellular differentiation, TNM staging for malignant tumors, disease-free survival, and overall survival in HCC." (PMID 27829832, 2016). "Building on the endogenous regulatory role of CCN3 on CCN2, a set of small modified peptides based on two CCN3 regions identified as responsible for this activity have been created by BLR Bio, as potential agents to treat fibrotic diseases including cancer." (PMID 32294968, 2020). "NOV/CCN3 is a secreted multifunctional protein belonging to the CCN family involved in different physiological and pathological processes such as angiogenesis, inflammation and cancers." (PMID 26367310, 2015). "In these cancers with common origin, a negative relationship between severeness and CCN3 expression levels was shown, suggesting that it results from the antiproliferative function of CCN3, but the pathological role of CCN2 still remains inconclusive." (PMID 35682564, 2022).
infection (5 papers, 2017 to 2024). The state of being infected such as from the introduction of a foreign agent such as serum, vaccine, antigenic substance or organism. "CCN3 decreased more significantly in response to infection in resistant (RBC) fish, perhaps contributing to observed fibrosis phenotypes." (PMID 34582586, 2021). "Meanwhile, CCN3 and PLTP were upregulated in patients with longer periods of infection which are involved in the negative regulation of inflammation." (PMID 37047248, 2023).
cardiovascular diseases (2 papers, 2020 to 2023). "It has been demonstrated that CCN3 plays a critical role in many diseases, such as central nervous system and cardiovascular diseases." (PMID 32455138, 2020). "On the basis of these findings, coupled with the established importance of innate immunity in a myriad of cardiovascular diseases, including CAVD, we speculated that myeloid CCN3 may affect the development of CAVD." (PMID 36670446, 2023).
immune diseases (1 paper, 2021). "Although CCN3 targeted therapy has not been used in clinical immune diseases, we believe that the application of the anti-CCN2 antibody in clinical trials will contribute to further clinical research of CCN3 to a certain extent." (PMID 34393649, 2021).
neurological disease (1 paper, 2020). "To this end, we conducted extensive profiling of CCN3 expression in healthy and MS disease states to answer whether CCN3 is dysregulated in MS and determine whether there is rationale for CCN3-mediated regenerative mechanisms as a therapeutic target for neurological disease." (PMID 33222687, 2020).
prostate (1 paper, 2017). "Previous studies have shown that CCN3 expression is upregulated in PCa cells and PCa patients, which suggests that CCN3 has a role in prostate tumorigenesis." (PMID 29088803, 2017).
renal diseases (1 paper, 2015). "Thus, the inhibition of NOV/CCN3 may represent a novel target for the progression of renal diseases." (PMID 26367310, 2015).
CCN3 also shares sentences with these, for which no sentence is quoted: chronic myeloid leukaemia (5 papers); autoimmune disease (2); Metabolic Disorders (2); mood disorder (2); neurodegenerative disease (2); viral infection (2); adrenocortical tumor (1); amyotrophic lateral sclerosis (1); aortic valve stenosis (1); bladder cancer (1); Cachexia (1); cardiac hypertrophy (1); cardiomyopathy (1); cataract (1); clear cell renal cell carcinoma (1); coronary artery disease (1); dilated cardiomyopathies (1); diverticular disease (1); fibrosis (1); intrahepatic cholangiocarcinoma (1); keloid (1); liver cancer (1); lung carcinoma (1); malignant adrenocortical tumors (1); metastasis (1); neuroblastoma (1); non-alcoholic fatty liver disease (1); ovarian serous cystadenocarcinoma (1); panic attacks (1); prostate tumors (1).
A further 5 diseases each share a sentence with CCN3 in 1 paper.